MTOR (mechanistic target of rapamycin kinase)
Diseases named in the same sentence as MTOR in open-access papers (continued):
Sharing a sentence is not in itself a finding about the gene and the disease.
Glucose intolerance (34 papers, 2012 to 2025). Glucose intolerance (GI) can be defined as dysglycemia that comprises both prediabetes and diabetes. "Sirolimus and everolimus, the mammalian target of rapamycin (mTOR) inhibitors used in KT, have also been associated with glucose intolerance, especially when administered with tacrolimus." (PMID 33800138, 2021). "Upstream to mTOR activation, the Forkhead box protein (FoxOs) family is associated with glucose intolerance as well as with CC tumorigenesis promotion." (PMID 30628165, 2019). "In pancreatic β-cells, loss of mTOR signaling with p70S6K has been shown to lead to hypoinsulinemia, glucose intolerance, insulin insensitivity to glucose secretion, and a decrease in β-cell size." (PMID 22545721, 2012). "However long-term and chronic mTOR inhibition by rapamycin or other rapalogs has been associated with glucose intolerance." (PMID 33691762, 2021). "Our results demonstrate that enhanced mTOR signaling is an important factor in age‐associated vascular dysfunction and may also play a role in glucose intolerance with aging." (PMID 27660040, 2017). "Periods of elevated mTOR activity can be detrimental and result in glucose intolerance by inhibiting the insulin receptor substrate 1 (IRS-1)." (PMID 37238686, 2023). "It has been reported previously that inhibition of mTOR signaling by rapamycin leads to glucose intolerance and insulin resistance." (PMID 28400571, 2017). "Next, we assessed whether enhanced mTOR signaling in the gut contributes to HFD-related glucose intolerance." (PMID 35440795, 2022). "This study also demonstrated that the PI3K/Akt/mTOR signaling pathway is activated, particularly the phosphorylation of Akt and mTOR, after α-LA supplementation; thus, this antioxidant may alleviate glucose intolerance in the liver damage in HFD-subjected rats." (PMID 38794739, 2024). "As proven in in vitro and in animal models, mTOR-Is may decrease beta-cell mass through an increment of the rate of apoptosis, induce impairment of glucose-induced insulin secretion, and facilitate glucose intolerance and insulin resistance." (PMID 37250653, 2023). "It has also been observed that long-term treatment with mTOR-Is (20 weeks) partially restored the detrimental effects on metabolism with enhanced insulin sensitivity, increased oxygen consumption, and improved serum lipid profile with a certain degree of glucose intolerance." (PMID 37250653, 2023). "Activation of mTOR promotes the secretion of insulin and increases insulin sensitivity; on the contrary, mTOR may lead to glucose intolerance through blocking of the insulin receptor substrate 1 (IRS1) by phosphorylation of p70S6K in a negative feedback loop manner." (PMID 31080547, 2019). "After 6 weeks of HFD, female mTOR-KOPlacenta displayed glucose intolerance but normal insulin sensitivity at 8 weeks of HFD treatment." (PMID 34032632, 2021). "It is important to note that although insulin is a potent activator of mTOR through Akt regulatory pathways, mTOR may have a negative feedback loop and led to glucose intolerance through inhibition of the insulin receptor substrate 1 (IRS1)." (PMID 22545721, 2012). "Despite the improved insulin signaling in the liver of rapamycin-treated rats, which came out from the blockade of the mTOR/S6K1 negative feedback loop, the induction of gluconeogenic pathway in the liver potentiates glucose intolerance." (PMID 30034573, 2018).
Arthritis (33 papers, 2008 to 2025). Inflammation of a joint. "Intracellular C3 convertase-independent C3a generation and C3aR activation contribute to homeostatic mTOR activity and T-cell survival, and increased intracellular C3 activation underlies T effector dysregulation in arthritis." (PMID 26787717, 2016). "mTOR inhibition has shown promise in reducing synovial inflammation, osteoclast formation, and protecting against bone erosions and cartilage loss in experimental arthritis models." (PMID 40589696, 2025). "Knockdown of Gal-9 alleviates the progression of arthritis in a collagen-induced arthritis (CIA) mouse model through the PI3K/AKT/mTOR pathway." (PMID 38957462, 2024). "Activation of IGF-1 receptor (IGF1R) promotes Akt-mTOR signaling, enhances glycolysis, and favors Th17 differentiation, impacting inflammatory processes such as arthritis through IL-6 modulation." (PMID 39200096, 2024). "Activation of AMPK and disruption of mTOR signaling have been shown to reduce inflammation in experimental arthritis." (PMID 39200096, 2024). "The anti-inflammatory effect of mTOR inhibition was also evident in 8–10 week-old IL1rn−/− mice with established arthritis." (PMID 36443301, 2022). "Using the glutamine antagonist 6-diazo-5-oxo-L-norleucine reduced Th17 splenic cells and suppressed arthritis when in combination with rapamycin (mTOR inhibitor) in a mouse model of disease." (PMID 35020864, 2022). "mTOR blockade with rapamycin inhibited arthritis and affected bone remodeling in a SpA rat model and also inhibited osteogenic differentiation of SpA patients' synovial fibroblasts in vitro." (PMID 33746955, 2021). "have shown that a combined inhibition of glutamine metabolism and mTOR significantly suppressed CD4+ T cell activation-mediated arthritis in mice better than each monotherapy, implying the essential role of cellular metabolism in immune cell mTOR signaling." (PMID 33897705, 2021). "Accumulating evidence has revealed that the Akt/mTOR signaling pathway plays a pivotal role in paeoniflorin-mediated numerous biological functions, such as arthritis, liver, and kidney diseases." (PMID 33240030, 2020). "In the HLA-B27 transgenic rat model of SpA, mTOR blockade reduces arthritis and spondylitis development and severity with decreased inflammation and bone defects with suppression of IL-17A." (PMID 32194539, 2019). "This study investigated how inhibiting both glutamine metabolism with 6-diazo-5-oxo-L-norleucine (DON) and mTOR with rapamycin affects immune cells and the arthritis in a mouse model." (PMID 31011190, 2019). "We demonstrate here for the first time that targeting mTOR by rapamycin, prophylactically and therapeutically, reduces the incidence and severity of arthritis and spondylitis." (PMID 32194539, 2019). "The aggregate of these observations establishes a robust evidentiary foundation for the legitimate extrapolation of in vitro findings to in vivo and clinical paradigms, thereby markedly enhancing the prospective utility of PI3K/AKT/mTOR-oriented strategies in the personalized treatment of arthritis." (PMID 40872543, 2025). "Metformin, the anti-diabetic drug, which indirectly activates AMPK, has been shown to mitigate disease in models of arthritis via the inhibition of mTOR pathway and the suppression of NF-κB-mediated inflammatory cytokine production, paralleled by enhanced autophagic flux." (PMID 35020864, 2022). "Previously, mTOR signaling has been shown to regulate osteoclastogenesis and osteoclast function, and in the pathological setting, the activation of mTOR is responsible for joint destruction in arthritis." (PMID 28793923, 2017). "This suppression dampens PI3K/mTOR/NF‐κB signaling, lowers inflammatory cytokine levels, and mitigates RA‐FLS invasiveness, ultimately alleviating arthritis symptoms." (PMID 40125636, 2025).
Arthritis (continued). "IL-1β induces inflammation, mitochondrial dysfunction and chondrocyte degeneration, while Sirt3 in arthritis treatment can ameliorate arthritis severity and joint damage through inhibition of the PI3K/Akt/mTOR pathway." (PMID 38913046, 2024). "Th17-focused therapy seems to show some promise as there is evidence of two patients, presenting with arthritis, ILD, and follicular bronchiolitis, having significant improvement of pulmonary involvement after treatment with mTOR inhibitor sirolimus." (PMID 39767180, 2024). "In general, berberine, palmatine, coptisine, jatrorrhizine, magnoflorine and jatrorrhizine hydrochloride in CC play the role in treating arthritis by regulating Wnt1/β-catenin and PI3K/AKT/mTOR signaling pathways." (PMID 37637408, 2023). "Paeoniflorin can regulate signaling pathways (GPCR pathway, MAPKs/NF-κB pathway, PI3K/Akt/mTOR pathway, JAK2/STAT3 pathway, TGFβ/Smads, etc.)in experimental arthritis FLS." (PMID 37033930, 2023). "At the molecular level, CC plays a critical role in the treatment of arthritis by regulating NF-κB, Wnt1/β-catenin and PI3K/AKT/mTOR signaling pathway, inhibiting the expression of IL-6, IL-1β, MMP-3 and TNF-α." (PMID 37637408, 2023). "This study found that inhibition of both pathways was more effective than inhibiting either mTOR or ERK alone and resulted in greatly decreased disease severity in a mouse model of arthritis." (PMID 24904823, 2014). "In conclusion, we reported here that rapamycin–metformin ameliorates arthritis and inflammation in vitro and in vivo while not inducing mitochondrial dysfunction, a potential side effect of mTOR inhibitors." (PMID 32276645, 2020). "For instance, inhibition of both the mTOR and MAPK (ERK) pathways using rapamycin and the MEK1/2 inhibitor PD325901 was identified as a means of robustly blocking effector CD4+ T cell proliferation in a mouse model of arthritis." (PMID 24904823, 2014). "In this study, we show that the mTOR inhibitor rapamycin and the glutamine antagonist 6-diazo-5-oxo-L-norleucine (DON), a glutamine analog that competitively inhibits the action of glutamine, act additively on immune cells and have a therapeutic effect on the arthritis in the SKG mouse model of RA." (PMID 31011190, 2019). "Although the upstream of mTOR in our data was not demonstrated, it is clear that down-regulation of mTOR-HIF-1α by EGCG contributed to reduction in Th17 and consequent amelioration of arthritis." (PMID 24558360, 2014).
fragile X syndrome (33 papers, 2012 to 2025). A genetic syndrome caused by mutations in the FMR1 gene which is responsible for the expression of the fragile X mental retardation 1 protein. "For instance, TSC, neurofibromatosis type 1 (NF1) and fragile X syndrome are all caused by mutations of mTOR-inhibiting genes, whereas rapamycin-induced mTOR inhibition prevents the proliferation of cytomegalic neurons and reduces episodic convulsions." (PMID 36675042, 2023). "One consistent finding in fragile X syndrome is the increased activity of the mechanistic target of rapamycin (mTOR) signaling pathway." (PMID 36504683, 2022). "Intriguingly, lithium treatment in a clinical trial and models of fragile X syndrome results in amelioration of behavioral abnormalities, decreased aberrant protein synthesis rates, and substantial decreases in mTOR activity." (PMID 36504683, 2022). "The association of abnormal mTOR activities (particularly hyperactivation) with different syndromic forms of ASDs, such as TSC, Fragile X syndrome, Angelman syndrome, Hamartoma tumor syndrome, and Rett syndrome, has been documented in many clinical studies." (PMID 35682995, 2022). "Furthermore, in addition to the genetic defect in Tsc1/2 and Pten, the lack of FMR1 expression, which leads to fragile X syndrome (FXS), an autism-associated disorder, also demonstrated hyperactive mTOR signaling both in KO mice and in FXS patients." (PMID 31849609, 2019). "The association of abnormal mTOR activities (particularly hyperactivation) with different syndromic forms of ASDs, such as TSC, Fragile X syndrome (FXS), Angelman syndrome, Hamartoma tumor syndrome, and Rett syndrome, has been documented in various clinical studies." (PMID 36045116, 2022). "Dysregulation of mTOR signaling has been found in Fragile X Syndrome." (PMID 36045116, 2022). "Deregulation of mTOR signaling has been identified as a phenotypic feature common to various forms of ASD, including fragile X syndrome, and mutations in tuberous sclerosis complex 1 and 2 (TSC1/2), neurofibromatosis 1, and phosphatase and tensin homolog (PTEN)." (PMID 30020076, 2018). "Various genetic diseases displaying a grave epileptic phenotype, like tuberous sclerosis, phosphatase and tensine homolog (PTEN)-hamartoma tumor syndromes and fragile X mental retardation syndrome (FXS), are associated with dysregulation of mTOR expression and activity." (PMID 27855659, 2016). "The misregulation of mTOR signaling was also observed in fragile X patients, suggesting that mTOR could be a target or biomarker for treatment of fragile X syndrome." (PMID 25767435, 2015). "The PI3K/Akt/mTOR signaling cascade has been implicated in the pathogenesis of various neurodegenerative and neuropsychiatric disorders, e.g., Alzheimer’s disease, Parkinson’s disease, epilepsy, tuberous sclerosis complex (TSC), fragile X syndrome, depression, schizophrenia and bipolar disorder." (PMID 36838876, 2023). "mTOR hyperactivity was observed for example in fragile X syndrome (FXS), neurofibromatosis 1 (NF1), tuberous sclerosis, and Opitz BBB/G syndrome." (PMID 34204880, 2021). "An increase in the levels of phosphorylated mTOR, S6K1, Akt as well as initiation factor 4E (eIF4E) has been observed in the protein lysates of individuals with fragile X syndrome." (PMID 36838876, 2023). "mTOR contributes to neurophysiological changes observed in models of ASD and fragile X syndrome (FXS)." (PMID 33132844, 2020). "The presence of abnormal mammalian target of rapamycin (mTOR) and related mTOR-mediated signaling has been demonstrated in several syndromic ASD models, including TSC, Fragile X syndrome, Rett syndrome, and Angelman syndrome." (PMID 30524240, 2018). "Inhibition of mGluR5 corrects symptoms of fragile X syndrome in adult mice and, importantly, reduces overactive ERK and mTOR signaling." (PMID 27855659, 2016).
fragile X syndrome (continued). "Altered mTOR signaling is a shared feature of many neurodevelopmental disorders that display high rates of mental retardation with comorbid autistic features such as TSC and fragile X syndrome (FXS)." (PMID 24806451, 2014). "The mTOR signaling pathway is a convergent pathway that is disturbed by genetic variations in the TSC1 and TSC2 (TSC), PTEN (Bannayan-Riley-Ruvalcaba syndrome, Lhermite-Duclos syndrome, and Cowden syndrome), FMRP (fragile X syndrome), and NF1 (neurofibromatosis type 1) genes." (PMID 36732866, 2023). "The interrelationship between hyperactivation of mTOR and different syndromic forms of ASDs such as TSC, fragile X syndrome (FXS), Angelman syndrome, and Hamartoma tumor syndrome, have been proven in various clinical investigations." (PMID 36838876, 2023). "The intricacy of GSK3, mTOR, and FMRP signaling, as well as their shared lithium sensitivity and functional overlaps, suggest that this signaling module may play a role in the effects of lithium in both fragile X syndrome and bipolar disorder." (PMID 36504683, 2022). "In Fragile X Syndrome (FXS), LTD is rendered mTOR-independent by hyperactive mGluR signaling." (PMID 23966835, 2013). "Notably, increased mTOR signaling and subsequent changes in global protein synthesis are shared molecular mechanisms of several rare neurodevelopmental disorders with an increased prevalence of ASD, such as fragile X syndrome (FXS)." (PMID 28775826, 2017).
cytomegalovirus infection (32 papers, 2012 to 2025). A herpesvirus infection caused by Cytomegalovirus. "This dysfunctional T-cell profile was associated with severe HCMV infection, while mTOR inhibitors were shown to enhance the proportion of functional T-cells." (PMID 37515280, 2023). "The mammalian target of rapamycin (mTOR) inhibitors is associated with a reduced risk of HCMV infection/disease in R+ recipients, which has also recently been shown in D+/R− recipients." (PMID 37515280, 2023). "Impaired OXPHOS function has been shown to stimulate the upregulation of the mechanistic target of rapamycin (mTOR) signalling pathway and mTOR activation has been implicated in cytomegalovirus infections." (PMID 32130224, 2020). "These proteins are members of the mTOR signaling pathway which has been implicated in human cytomegalovirus (HCMV) infection of mammalian cells and DENV infection of A. aegypti mosquitoes." (PMID 26859745, 2016). "There is now convincing evidence that immunosuppressive regimens, including mTOR inhibitors, are associated with less cytomegalovirus infection and disease." (PMID 24565283, 2013). "In addition, mTOR-inhibitor-based regimens have been shown to be associated with lower rates of post-transplant malignancy and less cytomegalovirus infection, which may add further to the appeal of this approach." (PMID 24565283, 2013). "Previous studies have shown that HCMV infection phosphorylates KAP1 via the mTOR pathway, as demonstrated using the mTOR inhibitor." (PMID 40267069, 2025). "The mTOR pathway is highly upregulated during HCMV infection and kinases within the signaling pathway are known to phosphorylate KAP1." (PMID 40267069, 2025). "mTOR inhibitors are appealing to physicians in decreasing the rate of cytomegalovirus infection and effective for post-surgery chylous pleural and peritoneal effusions." (PMID 33665195, 2021). "Among the family of FA elongases, ELOVL7 is increased more than 150-fold upon HCMV infection in an mTOR/SREBP-dependent manner." (PMID 31333664, 2019). "Although these two mTOR complexes normally differ in their substrate specificity and function, during HCMV infection, mTORC2 becomes involved in the phosphorylation of the mTORC1 substrates 4E-BP1 and S6K." (PMID 24945378, 2014). "While the UL38 protein appears sufficient to block the inhibitory effects of AMPK activation on mTOR activity, it is less clear how HCMV infection blocks AMPK's inhibitory effects on fatty acid biosynthesis." (PMID 22291597, 2012). "A recently conducted research demonstrated that HCMV infection may influence the proliferation of ECs through mammalian target of rapamycin (mTOR) signaling pathway." (PMID 32041970, 2020). "For the case-control analysis, regulation of gene expression (E2F targets, MYC targets), cell signal integration (mTORC1 signalling, PI3K AKT mTOR signalling) and immune response pathways were similarly identified (Browne HCMV infection, Bohn primary immunodeficiency syndrome)." (PMID 31719968, 2019). "As is the case for cytomegalovirus infection, clinical evidence indicate that the use of mTOR-based immunosuppressive regimens may be protective against BKPyV replication." (PMID 31394776, 2019). "In addition, cytomegalovirus infection, a deliberating issue in post-kidney transplantation, is decreased in mTOR inhibitors users." (PMID 30473931, 2018). "Additionally, HCMV infection reduces the levels of miR-100, and miR-101, which target components of the mammalian target of rapamycin (mTOR) complex, and delivery of unregulated mimics to replace these miRNAs leads to reduced HCMV replication." (PMID 28783105, 2017). "This warrants further studies to assess the positive impact of this and other mTOR inhibitors on the control of HCMV infection, whether after transplantation or in other settings." (PMID 25846574, 2015). "Thus, we hypothesized that kinase activated by the mTOR pathway phosphorylated KAP1 upon HCMV infection." (PMID 40267069, 2025).